DKC1 (dyskerin pseudouridine synthase 1)
Diseases named in the same sentence as DKC1 in open-access papers (continued):
Sharing a sentence is not in itself a finding about the gene and the disease.
cancer (continued). "Recently, the aberrant expression pattern of DKC1, NHP2, and NOP10 in several cancer entities has been reviewed." (PMID 33803145, 2021). "Genes of the DKC1 and TERT branches of the TEL-TMM were commonly up-regulated in all three cancer types, which resulted in the markedly increased PSF-score along these pathway branches." (PMID 31750255, 2019). "Using machine learning algorithms, including RF, SVM, GBM (XGBoost), and DT, the genes CDH3, DKC1, ESM1, MUSTN1, RCC2, TMT1A, and VEGFD were selected as key features from the tissue dataset to best discriminate between cancer and control samples and were used to design the predictive model." (PMID 40425785, 2025). "Current research suggests that “writer” regulators, mainly DKC1 and PUS enzymes, may help regulate cancer onset and progression, making them potential therapeutic targets for cancer treatment and prognosis." (PMID 39737343, 2024). "Notably, 40 DERIs were found to be specifically detected in the nuclear fraction, and many of these were from known cancer‐related genes, including AGRN, DKC1, PKMYT1, PLK1, and MARS1." (PMID 36461702, 2023). "A large proportion (47 RBPs) are commonly regulated in both RSCC and LSCC with several enriched for binding among DEGs (adj p < 0.05), including RBPs previously discussed in the context of CRC such MSI2, MEX3A, IGF2BP1/3, ELVAL4, and cancers in general, such as RBM47, DKC1, CELF4, ELAVL3." (PMID 32293332, 2020). "To determine whether DKC1 is involved in CRC development, we first assessed DKC1 protein expression in the tumour and paracancerous tissues of eight patients with cancer, its expression significantly increased in CRC tissues compared with normal tissues." (PMID 31857720, 2020). "However, the current understanding of DKC1 is relatively limited, and a comprehensive analysis of its role in cancer has not been conducted." (PMID 39103487, 2024). "The most-studied regulatory factor related to pseudouridine modification is Dyskerin Pseudouridine Synthase 1 (DKC1), which is a component of a small nucleolar ribonucleoprotein complex, needs RNA guidance to exert its catalytic activity, is overexpressed in various types of cancer." (PMID 35721510, 2022). "However, since the expression level of DKC1 is not considered, it is unknown whether pyrazofurin can treat cancer patients with DKC1 overexpression." (PMID 34778277, 2021). "The correlation of MYC with TERT and DKC1 in cancers suggests that oncogene activation is one of the important events that initiates cancer-specific non-telomeric functions of TERT and DKC1." (PMID 33599797, 2021).
tumor (54 papers, 2004 to 2026). "The expression of the DKC1 gene exhibited a positive correlation with the stage of 5 tumors, suggesting a potential association between the DKC1 gene and tumor progression." (PMID 39103487, 2024). "Subsequently, we investigated the association between DKC1 expression and the tumor microenvironment by employing the TIMER2.0 algorithm, which was further validated in 96 single-cell datasets obtained from the TISCH database." (PMID 39103487, 2024). "We also found a significant positive correlation between DKC1 expression and Tumor Mutational Burden in 14 tumors." (PMID 38082360, 2023). "Recently, many studies demonstrated that dysregulation of DKC1 was associated with tumor growth and metastasis as well as prognosis of patients suffering from various human cancer types, including brain, lung, breast, liver and colon." (PMID 37188742, 2023). "SUMOylation-deficient DKC1, however, showed little effect on the inhibition of tumor migration upon SENP3 overexpression." (PMID 37188742, 2023). "This study highlights the correlation between DKC1 expression levels in immune cells and their impact on tumor-associated fibroblasts." (PMID 38082360, 2023). "These in vivo data displayed that interfering circ-FLI1 caused tumor growth inhibition of CC by regulating miR-197-3p and DKC1." (PMID 35647294, 2022). "DKC1 mutations cause ribosomal dysfunction and result in a reduction of tumour suppressive proteins." (PMID 33317189, 2020). "Nuclear and nucleolar expressions of DKC1 protein were significantly associated with higher tumour grade (p < 0.0001), high nucleolar score (p < 0.001) and poor Nottingham Prognostic Index (p < 0.0001)." (PMID 32868896, 2020). "Notably, DKC1 promoter methylation was strongly associated with DKC1 mRNA expression in 24 tumor types." (PMID 39162904, 2024). "Only one report suggested that high DKC1 expression was strongly associated with adverse evnts and overall survival (P < 0.0001), the attenuation of keratin inhibits the proliferation and growth of tumor cells." (PMID 37426487, 2023). "Besides TERT, other genes encoding telomerase holoenzyme complex proteins such as DKC1 (Xq28), which we identified significantly upregulated in clinically aggressive tumours, and NHP2(5q35), are within the 5‐Mb‐ends of their respective chromosomes." (PMID 35979662, 2022). "Dyskeratosis congenit 1 (DKC1) is a tumor suppressor, and its gene mutation could cause cancer-prone syndrome; DKC1 regulates CC angiogenesis and metastasis." (PMID 35647294, 2022). "Our results indicate that changes in snoRNA levels are influenced by both host gene expression and DKC1 activity, suggesting coordinated regulation of snoRNA maturation and function in tumor cells." (PMID 41510246, 2025). "Various PUSs, including PUS7, PUS1, and DKC1, have been shown to regulate tumorigenesis by modulating tumor cell proliferation and apoptosis." (PMID 40260225, 2025). "In CRC, DKC1 promotes tumor angiogenesis and metastasis by directly activating HIF-1α transcription, with its high expression significantly linked to advanced TNM stage and poor prognosis." (PMID 41446042, 2025). "The most significant defects in DKC1-high tumors were highly reduced immune cell priming and activation (step 3), and the diminished trafficking of immune cells into tumor tissues (step 4)." (PMID 40458122, 2025). "The findings indicated that DKC1 was markedly increased in ESCC tissues when compared to adjacent non-tumour samples." (PMID 39103487, 2024). "To explore potential therapeutic strategies that can counteract the tumor-promoting effects mediated by DKC1, we conducted CMap analysis." (PMID 39103487, 2024). "We then validated the difference in the expression of DKC1 between tumor and normal tissues via three-dimensional multiomics difference analysis." (PMID 39103487, 2024).
tumor (continued). "Recent research has shown that the DKC1 gene is highly expressed in various tumors and influences tumor proliferation and metastasis." (PMID 39103487, 2024). "In colorectal cancer (CRC) patients, depletion of the synthetase DKC1 leads to increased attenuation of the mRNA expression of several ribosomal proteins, thereby mediating tumor cell growth." (PMID 39162904, 2024). "To analysis the DKC1 role in tumor diseases, we analyzed the DKC1 expression level according to the amount of RNA expression with the help of HPA database." (PMID 38082360, 2023). "For example, DKC1 overexpression in prostate cancer was necessary for extensive tumor growth, possibly due to its critical function in sustaining protein biosynthesis." (PMID 37612540, 2023). "Immunohistochemistry of DKC1 in transplanted tumor tissue showed that the expression of DKC1 in shDKC1 group was significantly lower than that in NC group." (PMID 37426487, 2023). "We performed two DKC1 knockout cell lines to explore the correlation of DKC1 expression level and tumor cell proliferation rate." (PMID 38082360, 2023). "The tumor cases were divided into two groups based on their DKC1 expression status, namely low and high DKC1 groups." (PMID 38082360, 2023). "In vivo experiments showed that tumor growth of DKC1 knockout mice was slower and the volume was significantly smaller than that of the control group." (PMID 37426487, 2023). "Recent research has revealed the role of dkc1 in controlling the proliferation, migration, and invasion of tumor cells." (PMID 37570350, 2023). "The tumor-bearing mouse model was constructed, shDKC1 was transfected to observe the tumor growth and tumor tissue changes, and the expression of DKC1 and Ki-67 was detected." (PMID 37426487, 2023). "We retrieved the top 50 interacting proteins and the top 100 linked proteins to WDR12 in tumor tissue from the STRING and GEPIA2 databases, respectively, and found that DKC1 is a promising candidate." (PMID 36726716, 2022). "Computational analysis has also shown the upregulation of several H/ACA snoRNAs and amplification of DKC1 in metastatic tumours compared to primary tumours." (PMID 35205419, 2022). "Western blotting data showed that DKC1 protein expression was inversely modulated by miR-197-3p and was highly expressed in human CC cell lines and tumor tissues." (PMID 35647294, 2022). "As a consequence, DKC1 inhibition (knockdown or PF treatment)‐induced unexpected activation of the tumor‐promoting RAS‐ERK pathway would largely counteract the antitumor effects." (PMID 34026451, 2021). "Pathological analyses showed that the DKC1 knockdown tumor cells express less proliferation marker Ki67 compared to control cells, and there are more DNA damage marker γH2A.X positive cells in DKC1 knockdown tumors." (PMID 33879171, 2021). "Increasing evidences have suggested an association between abnormal expression of Ψ synthases (such as PUS1, PUS7, PUS10 and DKC1) and tumor malignant progression." (PMID 35118063, 2021). "At the end of the experiment, the tumor weight of DKC1 knockdown PC-9 cell group is lighter than the control group." (PMID 33879171, 2021). "The detectable tumor for DKC1 silenced PC-9 cells emerged at day 18, which is significantly later than control cells (day 9)." (PMID 33879171, 2021). "CD31 for assessing tumour angiogenesis and Ki67 for assessing tumour proliferation were also reduced in DKC1 knockdown xenograft tumour." (PMID 31857720, 2020). "At the optimal DKC1 cut-off values (H-score 110 and 10, respectively), High DKC1 nuclear and nucleolar expression were observed in 574/942 (61%) and 153/942 (16%) of the informative tumours, respectively." (PMID 32868896, 2020). "DKC1 knockout inhibits tumor proliferation, migration, and invasion by regulating the NF-κB/MMP-2 signaling pathway in vitro." (PMID 32528520, 2020).
tumor (continued). "Our data exhibited a significant decrease in the weight and volume of the tumours with DKC1 stable knockdown cells compared with the control cells." (PMID 31857720, 2020). "IHC assay showed that the DKC1 knockdown xenograft tumour HIF-1α and VEGF protein expression was decreased compared with the control group." (PMID 31857720, 2020). "Transwell assay showed that the capacity of tumour cell migration and invasion was dramatically reduced when DKC1 decreased in HCT116 and DLD1 cell lines." (PMID 31857720, 2020). "In vitro experiments showed that the loss of DKC1 function affects telomerase activity by reducing hTR levels, leading to premature telomere shortening that may result in chromosomal end-to-end fusions, breakage and rearrangements associated to tumor development." (PMID 28666010, 2017). "In these studies, increased DKC1 expression was related to markers of tumour proliferation, like high TERC, MKI67 and MYC levels." (PMID 26366868, 2015). "Kaplan–Meier analysis revealed a marked, but not significant (log-rank: P=0.140), difference in the clinical course between tumours, with DKC1 expression above vs below median." (PMID 19755982, 2009). "DKC1-mediated tumor intrinsic and extrinsic mechanisms drive poor patient outcomes." (PMID 40458122, 2025). "DKC1 promotes tumor spread, invasion, and migration; PUS7 promotes cell growth and self-renewal." (PMID 41446042, 2025). "Increased DKC1 expression was observed in high tumor stages (T3/T4)." (PMID 40458122, 2025). "The findings indicate that high DKC1 expression contributes to immune cold tumor environment." (PMID 40458122, 2025). "Our findings demonstrated that DKC1 knockdown significantly inhibited tumor growth in nude mice." (PMID 39103487, 2024). "In addition, DKC1 exhibited higher expression in glioma and accelerate tumorigenesis and tumor metastasis." (PMID 38376551, 2024). "Lastly, through in vivo experiments, it was demonstrated that DKC1 strengthened tumor growth." (PMID 38376551, 2024). "Overall, DKC1 exhibited high expression in all tumor tissues within the database." (PMID 39103487, 2024). "In all tumor types, the expression of DKC1 was strongly correlated with MYC-TARGETS_V1 activation." (PMID 39162904, 2024). "By impairing the processing of rRNA precursors, DKC1 can act as a tumor suppressor." (PMID 38082360, 2023). "In this study, downregulation of DKC1 expression could inhibit the expression of KI-67 and tumor proliferation." (PMID 37426487, 2023). "These apparently contradictory functions could reflect cell-specific balances of different DKC1 functions in each tumor type." (PMID 36732018, 2023). "DKC1 assumes an indispensable role as a constituent of the telomerase complex, with its participation being crucial in the post-transcriptional processing of precursor rRNA, thereby exerting a pivotal influence on the progression of tumor cells." (PMID 37502362, 2023). "The expression of DKC1 may impact patient survival by altering the immune infiltration of tumor cells." (PMID 38082360, 2023). "Interestingly, TERC and DKC1 overexpressions were observed to co‐occur in aggressive TCs,9 which raises the possibility of DKC1‐mediated stabilization of TERC RNA in these tumours." (PMID 36394204, 2022). "Moreover, the expression of circ-FLI1 was downregulated in xenograft tumor tissues and allied with higher miR-197-3p and lower DKC1." (PMID 35647294, 2022). "Results supported that DKC1 expression can be used as a tumor marker for CRC." (PMID 35484099, 2022). "The tumor growth is much slower in DKC1 silenced PC-9 cells compared to control cells." (PMID 33879171, 2021). "Moreover, this study has explored the oncogenic function of DKC1 both in vitro and in vivo and the potential mechanism of DKC1 promoting tumor progression." (PMID 33879171, 2021). "Further studies will be required to fully explore whether DKC1 has a pro-oncogenic or tumour suppressive role." (PMID 33461542, 2021).
tumor (continued). "In the GSE59612 dataset, the expression of PUS1, PUS7, RPUSD1 and DKC1 were significantly increased in the tumor core tissues relative to tumor marginal tissues and paracancerous tissues; and the expression of TRUB1 was decreased from paracancerous tissue to tumor core tissue." (PMID 35118063, 2021). "Subcutaneous tumour model also showed that DKC1 knockdown significantly inhibited tumour size." (PMID 31857720, 2020). "Therefore, the alterations in DKC1 and scaRNA expression observed in tumor cells could ultimately contribute to their splicing profile and constitute a new route implicated in GBM development." (PMID 41510246, 2025). "Furthermore, we observed varying levels of DKC1 expression across different tumor types." (PMID 39103487, 2024). "Interestingly, when patients were stratified by the expression of SENP3, DKC1 lost its role as an indicator for poor outcomes among patients with lower expression of SENP3, implicating that SUMOylated DKC1 might exert a more robust pro-tumor effect." (PMID 37188742, 2023). "In addition, we studied the development of NB tumor in vivo, and the results showed that when DKC1 was knocked out, the tumor volume was significantly smaller than that of the control group, and the tumor growth curve was significantly lower than that of the control group." (PMID 37426487, 2023). "To test whether DKC1 also affected clonogenicity, we performed 3D tumor spheroid assays." (PMID 36732018, 2023). "DKC1 is overexpressed in multiple malignancies such as CRC, HCC, NBL, and BC, where its upregulation is correlated with enhanced tumor invasiveness and poor prognosis." (PMID 41446042, 2025). "The present findings unravel genomic alteration- and sex hormone-mediated dysregulation of the telomerase cofactor DKC1 in UCEC tumors, and its upregulation participates actively in the UCEC pathogenesis through tumor-intrinsic and extrinsic mechanisms." (PMID 40458122, 2025). "Concurrently, DKC1-mediated Ψ modification and NAT10-catalysed ac4C modification further promote tumor progression by influencing rRNA function and enhancing mRNA stability, respectively." (PMID 41446042, 2025). "To examine the impact of DKC1 on the proliferative capacity of ESCA in vivo, we established a nude mouse subcutaneous transplantation tumor model by injecting the stable human cell lines EC9706-shNC and EC9706-ShDKC1." (PMID 39103487, 2024). "Our results disclosed that DKC1 exhibited higher expression, and DKC1 upregulated TNFAIP6 expression to aggravate the tumor growth and metastasis in GC." (PMID 38376551, 2024). "The increased expression of DKC1 with reduced macrophages and CD8+ T-cells infiltration is consistent with the concept that appropriate immune surveillance is required for tumor control." (PMID 36428700, 2022). "We measured the correlation of DKC1 expression with CD8+ T cells at tumor sites, stromal sites, and the invasive front (where the tumor invaded the normal lamina propria)." (PMID 36428700, 2022). "We also identified an overexpression of DKC1, the catalytically active component of the H/ACA box snoRNP in NSCLC tumor samples." (PMID 33288886, 2021). "Regarding the association with the intrinsic PAM50 subtypes, high expression of DKC1 mRNA was observed in basal-like, HER2+ and Luminal B tumours (p < 0.0001)." (PMID 32868896, 2020).